CD4 (CD4 molecule)
Diseases named in the same sentence as CD4 in open-access papers (continued):
Sharing a sentence is not in itself a finding about the gene and the disease.
AIDS (continued). "However, a person is said to be diagnosed with AIDS, only when the CD4+T cell count drops below 200 cells/microlitre, time period for which is indefinite and may last from few months to years." (PMID 23483108, 2013). "However, using CD4 cell count to guide intermittent therapy starting and stopping points, the SMART study (strategies for management of antiretroviral therapy), revealed that STI were associated with increased risk of AIDS and other complications." (PMID 23844869, 2013). "In addition, studies from our laboratory have identified a dramatic CD4 T cell loss (<50 cells/μl of blood) within a cohort of experimentally SIV infected mangabeys, which have remained free of clinical AIDS for greater than 11 years despite this paucity of CD4+ T cells." (PMID 23825945, 2013). "The understanding of whether or not APFP is associated with lower or higher CD4+ T cells counts is of utmost importance for the management of patients in the context of HIV/AIDS." (PMID 23710648, 2013). "Event rates in CD4 strata among the 75,336 patients with at least one suppression episode while on cART: event rates per 1,000 y of suppressed viral load (number of events) for a first new AIDS event, with each event then classified as either an opportunistic infection or a HIV related neoplasm." (PMID 22448150, 2012). "Nevertheless, other record linkage studies of cancer registries with cohorts of HIV-infected persons and/or AIDS registries have failed to observe any link between CD4+ cell counts and lung cancer risk, or any change in risk between the pre-combined antiretroviral therapy (cART) and cART era." (PMID 22240797, 2012). "Thus, the decline of CD4+ T cells results in an impaired immune system and the progression of infection (the main consequence of the onset of opportunistic infections) to AIDS (human immunodeficiency syndrome) and death due to conditions associated with infection." (PMID 23251108, 2012). "While it seems likely that at least some patients who are LTFU have died without this information reaching the site, the lack of association between key measures of HIV disease progression, such as CD4 count and AIDS defining illnesses, and LFTU suggests it may be lower than in African settings." (PMID 22461979, 2012). "This hypothesis is supported by results showing that the pool of TCM cells is a correlate of anergy towards the viral antigens in Macaca mulatta but not in Cercocebus atys, which is naturally resistant to CD4+ T-cell loss and full-blown AIDS." (PMID 22737073, 2012). "However, after adjustment for time-updated CD4 count, use of cART, viral load and other factors, regional differences in AIDS related mortality were still significant, indicating that the differences cannot be fully explained by those variables collected and included in our models." (PMID 22911841, 2012). "Furthermore, initiation of anti-retroviral therapy in AIDS patients showed a decrease in the biomarker levels similar to changes in viral load and CD4 counts and specific biomarker levels have been demonstrated in various studies to be independently predictive of progression or development of AIDS." (PMID 22970212, 2012). "Nevertheless, we cannot exclude that a small number of advanced AIDS patients with CD4>200 cells/μl or VL>400 copies/mL were misclassified as recent infections which could lead to an overestimation of both the prevalence of recent infected patients and median HIV-RNA levels." (PMID 22363755, 2012). "It is currently recommended that people start cART when their CD4 count falls below 350 CD4 cells per cubic milliliter (cells/mm3) of blood, when they develop severe constitutional symptoms such as fever lasting longer than a month, or when they develop an AIDS-defining condition." (PMID 22479156, 2012).
AIDS (continued). "Furthermore, not all virologically suppressed patients are able to effectively recover their CD4+ T-cell count, thus exposing immunologic nonresponders to a significant risk of both AIDS-related and non-AIDS-related morbidities." (PMID 22489250, 2012). "Decreased CMI is the hallmark of HIV-associated immune dysfunction, and responses to HBV vaccine are dependent on T-cell help, but we found HBV vaccine responses were associated with the risk of AIDS/death independent of CD4 cell count, and a marker of CMI, DTH responses." (PMID 22457767, 2012). "However, multiple factors may influence this immunologic response, including CD4+ nadir, a preceding AIDS diagnosis, and, importantly, time from HIV infection to HAART start." (PMID 21244701, 2011). "Such subjects are commonly defined as "AIDS presenters" when the diagnosis of HIV-1 infection is concurrent with an AIDS-defining opportunistic disease (Group C according to the Centers for Disease Control classification system) or with a number of CD4+ T cells near or below 200/μL." (PMID 22166160, 2011). "In addition, our analysis indicates that a variety of other factors may affect and modulate the CD4+ response curve, including nadir CD4+ cell count, AIDS prior to HAART start and pre-HAART duration of HIV infection." (PMID 21244701, 2011). "CMV retinitis, one of the major opportunistic infections of HIV/AIDS, will remain a clinical problem and cause of avoidable mortality and blindness until there is widespread early detection of HIV infection and early initiation of antiretroviral therapy at higher CD4 counts." (PMID 21843351, 2011). "Explanations include decreased gastric acid secretion predisposing to gastric colonization by other microorganisms that might compete with H. pylori, the use of either antibiotics or PPI and, as suggested in other studies, the low count of T CD4 cells in AIDS patients." (PMID 21333017, 2011). "Since IFNα inhibits cell proliferation and modulates immune responses, chronically high levels of this cytokine in LN of HIV-1 patients may impair differentiation and immune function of bystander CD4+ T cells, thus playing into the mechanisms of AIDS immunopathogenesis." (PMID 20559432, 2010). "However, a few exceptions have been noted in which CXCR4 use emerged following experimental infection, which was associated with profound CD4+ T cell loss although not clinical AIDS." (PMID 20865163, 2010). "These factors could explain why AVL/HIV-AIDS patients already had CD4 cell counts lower than 200 cells/mm3 at the beginning of anti-leishmanial therapy (data not shown), which additionally could contribute to the maintenance of low levels during remission phase." (PMID 21171992, 2010). "While virus-induced cell death might explain early loss of CD4+ T cells, such mechanisms were unlikely to explain the slow depletion over the long period leading to AIDS." (PMID 19360097, 2009). "However, during the prolonged observation (at month 15, month 21 and month 33 visits), significant less fractions of subjects from HIV/HCV dual infection or HIV/HCV/Toxoplasma triple infection progressed into AIDS stage defined as CD4+ T cells below 200 cells/μl." (PMID 19098990, 2008). "SHIVSF162P3 induces gradual CD4+ T-cell loss and causes AIDS in some but not all rhesus macaques." (PMID 18928523, 2008). "Kaplan-Meier survival analysis and Cox proportional hazard models showed that frequencies of cytokine-producing Gag-specific CD8+ T cells (IFNγ, IL-2 or both) shortly after seroconversion were neither associated with time to AIDS nor with the rate of CD4+ T-cell decline." (PMID 18648514, 2008). "Thus, circulating Mo are a minor reservoir for HIV compared to CD4+ T-cells in AIDS patients." (PMID 18575590, 2008). "Finally, we analyzed whether a combination of relatively high CD4+ and high CD8+ T-cell responses one year after seroconversion was associated with slow progression to AIDS." (PMID 18648514, 2008).
AIDS (continued). "Thus, the plasma HIV RNA level, as a predictor of future progression to AIDS or death, might be less important than the CD4 cell count." (PMID 16710078, 2006). "Moreover, all patients had CD4+ ≤300 cells/μL and a diagnosis of AIDS at some point." (PMID 16839416, 2006). "Using the technique of holistic medicine based on the life mission theory and the holistic process theory of healing, we hypothesize that the improvement of QOL can have sufficient biological effect on the CD4, which could avoid or postpone the development of AIDS." (PMID 15167940, 2004). "Multivariable analysis showed greater odds of TB diagnosis among males, those with low BMI, prior AIDS diagnosis, high HIV viral load, low CD4+ counts, or low total cholesterol." (PMID 40965078, 2026). "A 43-year-old man presenting with AIDS (HIV-RNA 8.48 × 106 copies/mL; CD4+ 20 cells/μL) was admitted with disseminated tuberculosis and multiple bowel perforations requiring urgent surgery." (PMID 41893121, 2026). "More than one third (37%) of the patients who died had a CD4 cell count below 200 cells/μL at the time of HIV diagnosis, but only 10% of those patients had an AIDS-defining illness at the time of HIV diagnosis (according to the CDC definitions)." (PMID 41597637, 2026). "Variables with p < 0.10 in univariate analysis included sex, age, smoking status, BMI, hepatitis C co-infection, HIV exposure mode, ART combination, prior AIDS diagnosis, HIV viral load, CD4+ cell count, and total cholesterol." (PMID 40965078, 2026). "Compared to HIV-1, HIV-2 infection is characterized by lower viral loads and slower decline in CD4 cells, however the majority of people living with HIV-2 (PLWH2) progress to AIDS and will benefit from antiretroviral therapy." (PMID 41637462, 2026). "CD4+ T cells are central regulators of adaptive immune responses, and their depletion following HIV infection leads to AIDS." (PMID 41910361, 2026). "Additionally, this study represents the first identification of a transcriptional signature associated with a reduced CD4:CD8 T cell ratio, and as such, this work may shed light on the molecular basis for how this ratio is associated with non-AIDS comorbidities in PWH." (PMID 39990376, 2025). "The incidence of AIDS events was, as expected, increased after NHL and KS, reflecting the often-close connection to recently diagnosed HIV with high VL, low CD4 count and other viral coinfections." (PMID 41463249, 2025). "This network meta-analysis (NMA) aimed to compare CM interventions for enhancing CD4+ T-cell counts and overall efficacy in HIV/AIDS management." (PMID 41262939, 2025). "Antiretroviral therapy (ART) effectively suppresses viral load, slows CD4+ T cell depletion, and partially restores the CD4/CD8 ratio, thereby delaying the progression to acquired immunodeficiency syndrome (AIDS)." (PMID 41189709, 2025). "Low adherence to ART leads to increased viral load and decreased CD4 T-cell count, accelerating HIV progression to AIDS." (PMID 39752996, 2025). "The CD4:CD8 ratio has been previously shown to be predictive of mortality and non-AIDS morbidity for PWH, even during suppressive ART." (PMID 39990376, 2025). "Senescence of T cells was more accentuated in AIDS/VL than in HIV subjects in our study, although CD4+ T cell counts were significantly higher in the HIV group." (PMID 40096173, 2025). "Special attention should be given to the category of ECs who exhibit a gradual clinically significant decrease in CD4+ T cells, where initiating ART should definitely be considered to prevent AIDS-related illness." (PMID 40599486, 2025). "We analyzed CD4+ and CD8 +T cell activation and senescence in HIV, asymptomatic HIV-L. infantum co-infection, AIDS/VL co-infection, as well as, immunocompetent groups, active symptomatic VL, Recovered VL, DTH+ and healthy subjects." (PMID 40096173, 2025). "At the same time, CD4+ T counts were higher in HIV and in Asympt HIV/Leish individuals than in AIDS/VL." (PMID 40096173, 2025).
AIDS (continued). "Linked data include overlapping clinic and surveillance data, such as demographics, mode of HIV transmission, dates of diagnosis for HIV and AIDS, and HIV-related laboratory results, including CD4 T-lymphocyte (CD4) counts and HIV viral loads." (PMID 40811829, 2025). "The CD4/CD8 ratio has emerged as a marker for immune activation and aging, with relevance for non-AIDS comorbidities in treated HIV patients." (PMID 39852084, 2025). "AIDS is characterized by immune system dysfunction due to HIV infection, which leads to the destruction of CD4+ T cells and compromises the immune response." (PMID 40642477, 2025). "Immunological markers (CD4 cell count) are used in Ethiopia to decide on initiation of antiretroviral therapy and monitor HIV/AIDS disease progression." (PMID 40260411, 2025). "CD4+ cell counts were measured within the first two months after both the diagnoses of fungal infections and of HIV/AIDS." (PMID 40943696, 2025). "Previous studies have demonstrated that CM therapeutics can increase CD4+ T-cell counts and improve the immunological function of patients with HIV/AIDS, with a particular focus on its promotion of patients' immune reconstitution." (PMID 41262939, 2025). "Another important limitation of the available evidence is the inconsistent reporting of HIV-related immunologic variables, including viral load, CD4/CD8 ratio, and AIDS status." (PMID 41304899, 2025). "Higher percentages of CD4+ or CD8+T cells expressing markers CD57+ (senescence) or PD1+ (marker of activation or exhaustion) were observed in asymptomatic HIV/Leish and AIDS/VL subjects compared to other groups." (PMID 40096173, 2025). "Effective management of HIV/AIDS relies on adherence to ART, ensuring optimal control of viral load and CD4 levels while preventing further complications." (PMID 39761261, 2025). "Peripheral blood lymphocyte subset analysis revealed profound depletion of CD3+ CD4+ T-cells (0.01%; reference range: 27%–51%) and complete inversion of the CD4+/CD8+ T-cell ratio (0.00), consistent with WHO Stage 3 HIV/AIDS." (PMID 40980170, 2025). "Hence, perforin is critical to regulate homeostatic proliferation and the function of DCs, CD8+ and CD4+T cells to avoid their overaccumulation and functional dysregulation, which is responsible for immunopathologic symptoms during infectious and inflammatory diseases, and AIDs." (PMID 41009359, 2025). "CD4 metrics—absolute count, CD4%, and the CD4/CD8 ratio—are essential for assessing immune health and managing HIV/AIDS." (PMID 39852084, 2025). "As such, CD4+ T cell quantification is essential for staging HIV infection and AIDS, as well as monitoring treatment response." (PMID 41041302, 2025). "The incidence of LLV among people living with HIV/AIDS treated with INSTI-sparing regimens in Guizhou Province is relatively high and is mainly influenced by factors such as age, CD4+ T lymphocyte count and treatment regimens." (PMID 40809772, 2025). "IRIS is typically observed in HIV/acquired immunodeficiency syndrome (AIDS) patients during the initial months of highly active antiretroviral therapy (HAART), where it is believed to result from an exaggerated immune response to opportunistic pathogens as CD4+ T cell counts recover." (PMID 40149973, 2025). "These proportions are similar to the official report on the proportion of patients with < 200 CD4 + T cells by the National Center for Prevention and Control of HIV/AIDS (CENSIDA)." (PMID 39966809, 2025). "Additionally, some patients may be diagnosed even later, classified as having advanced disease with an initial CD4 T count of less than 200 cells/mm3 or the presence of an AIDS-defining illness, leading to a markedly worse prognosis and even lower survival rates." (PMID 40559606, 2025). "As microfluidic POC devices continue to evolve, they have the potential to democratize access to CD4 monitoring, significantly improving patient outcomes and advancing global HIV/AIDS management." (PMID 39852084, 2025).
AIDS (continued). "CSF was positive for VZV (via BioFire) and EBV (by PCR), with a concurrent HIV-1 viral load of 84,600 copies/mL and a low CD4 count, consistent with VZV and EBV coinfection in the setting of AIDS." (PMID 40959339, 2025). "Our study showed lower ex vivo activation of both CD4+ and CD8+ T cells in DTH+ or recovered-VL subjects than those with Asympt HIV/Leish or AIDS/VL, although the former groups have been shown to mount specific T cell response after stimulation." (PMID 40096173, 2025). "The average estimated duration of HIV was 10 years, 56.5% had a prior diagnosis of AIDS, 355 (66.9%) took ART at baseline, the plasma HIV RNA was ≤ 200 copies/mL in 248 (46.7%), and nadir and current CD4 + T lymphocyte count (median [IQR]) was 173 and 448/μL." (PMID 40195986, 2025). "The present study investigated the effect of H. pylori infection on CD4+ T cell counts and HIV viral load levels, which are the most important and widely used predictors of progression to AIDS, among people infected with HIV in a high co-endemic setting." (PMID 38494500, 2024). "The main purpose of this study was to investigate the determinants of longitudinal changes in CD4 cell count and survival time to death among HIV/AIDS patients as adults from January 2016 to December 2019 at Yabelo General Hospital." (PMID 38913649, 2024). "An absolute CD4+ count of 2/μL indicated advanced HIV and AIDS, necessitating a multidisciplinary approach to care." (PMID 39233730, 2024). "Our main findings were that PLHIV with the outcome had lower CD4 counts at ART initiation, had more often already developed an AIDS event before ART was initiated and more often were intravenous drug users compared to those without the outcome." (PMID 38381307, 2024). "Some factors have been analyzed and only HIV /AIDS stage show positive correlation to the severity of DSP, in contrary with CD4 levels, ARV, BMI and hemoglobin levels." (PMID 39315066, 2024). "Levels of CD3+, CD4+, CD4+/CD8+, B cells and NK cells in patients with AIDS were significantly lower than those in asymptomatic patients, while the level of CD8+ was significantly higher (P<0.05), Table-III." (PMID 39554636, 2024). "CD4+ T cells are essential for adaptive immunity, their depletion, as seen in HIV-induced AIDS, leads to immunodeficiency, whereas their improper activation can trigger autoimmune disease." (PMID 39416278, 2024). "In our motivating example from the epidemiology of HIV infection, EHR longitudinal data from the Athens Multicenter AIDS Cohort Study (AMACS) are available, with special focus on the number of CD4 cells, an immunological marker of HIV disease progression." (PMID 39449049, 2024). "The results of the median CD4 counts obtained in our study are comparable to those reported in the epidemiological surveillance report on HIV and AIDS in Spain in 2020 (345.0 vs. 371.0)." (PMID 38338246, 2024). "The CD4 model allowed for group-specific slopes (MSM and PWID) and was adjusted for age at ART initiation, AIDS occurrence before ART, and year of HIV diagnosis." (PMID 39449049, 2024). "Regarding HIV parameters, populations with the lowest risks of HIV/AIDS mortality, including PWH with higher ART adherence, engagement in care and initial CD4 counts, lose the most life expectancy from smoking and gain the most from smoking cessation." (PMID 38924347, 2024). "Although recent versions of guidelines in a number of countries recommend immediate initiation of ART for HIV/AIDS, the previous recommendations have had a noticeable impact on the timing of ART initiation and CD4 cell counts in PWH over the past two decades." (PMID 38778273, 2024). "Acquired immunodeficiency syndrome (AIDS) is a consequence of the tropism of HIV, which targets CD4+ T cells." (PMID 39459974, 2024). "A baseline CD4 cell count < 200 cells/uL, history of TB, Hgb level < 10 g/dL, BMI < 18.5 kg/m2, and not receiving IPT are independent predictors of TB among HIV/AIDS patients." (PMID 39234419, 2024).